TNF (tumor necrosis factor)
Diseases named in the same sentence as TNF in open-access papers (continued):
Sharing a sentence is not in itself a finding about the gene and the disease.
autoimmune disease (continued). "However, under anti-TNF-α therapy some patients show increased disease activity or even the onset of new autoimmune diseases, such as our patient, who developed VKHLD." (PMID 41142785, 2025). "This led us to a hypothesis explaining the paradox of inducing autoimmunity by TNF-blockade in context with IL-17-mediated autoimmune diseases and an explanation why VKHD should be treated with anti-IL-17A/F rather than with anti-TNF-α." (PMID 41142785, 2025). "Tumor necrosis factor-alpha (TNF-α) is a cytokine with multiple effects on different cell types, recognized as a key regulator of inflammatory and oxidative responses and implicated in the pathogenesis of various inflammatory and autoimmune diseases." (PMID 40430395, 2025). "While TNF-α blockade has been effective in reducing inflammation and improving clinical outcomes in autoimmune diseases, it is important to note that some patients treated with selective TNF inhibitors may develop autoantibodies." (PMID 39900937, 2025). "Since other autoimmune diseases are usually induced earlier under TNF-alpha blocking therapy, we speculate that the Patient’s flu-like infection could have initiated an unspecific stimulation and dysregulation of her immune system." (PMID 41142785, 2025). "Furthermore, moderate exercise has anti-inflammatory effects in various diseases, and meta-analyses have shown that regular exercise can reduce levels of inflammation-related markers in autoimmune diseases, such as C-reactive protein, TNF-α, and IL-6." (PMID 41347064, 2025). "TNF-α orchestrates the progression of autoimmune disease by inducing apoptosis or by activating the NF-κB pathway for inflammatory gene activation; it exists in either soluble or membrane-anchored form, both of which can interact with TNFR1 and TNFR2 to induce inflammatory signaling cascades." (PMID 40338229, 2025). "Several studies suggest that anti-TNF therapy may affect cardiovascular outcomes in patients with autoimmune diseases." (PMID 40648921, 2025). "TNF-α, a key cytokine, plays a significant role in autoimmune diseases, with TNF-α inhibitors revolutionizing their treatment; they achieve this by impairing insulin signalling by increasing the serine phosphorylation of insulin receptor substrates, leading to decreased insulin sensitivity." (PMID 40407536, 2025). "TNF-α is a pro-inflammatory cytokine that is critically involved in autoimmune diseases." (PMID 40283142, 2025). "However, in a proinflammatory environment, as observed in a mouse model of autoimmune disease, primary biliary cholangitis, Man impairs the production of TNF‐α, IL‐1β, Arg1, and IL‐6 cytokines." (PMID 39950558, 2025). "Notably, cases of sarcoidosis in patients with autoimmune diseases who were receiving anti-TNF-α agents have been reported." (PMID 41357198, 2025). "However, under pathological conditions such as autoimmune diseases, the synergy between IL-17A and other pro-inflammatory cytokines – including TNF, IL-1, and IFN-γ – amplifies inflammatory responses, ultimately leading to tissue damage." (PMID 40469524, 2025). "Furthermore, the clinical use of TNF inhibitors—commonly prescribed for autoimmune disorders—demonstrates the delicate balance of TNFR-mediated immune regulation." (PMID 40299450, 2025). "TNF-α participates in the pathogenesis of some inflammatory and autoimmune diseases, triggering various inflammatory molecules, including other cytokines and chemokines such as IL-6, a soluble mediator with pleiotropic effects on inflammation, immune response, and haematopoiesis." (PMID 38790615, 2024). "The medical literature has documented instances where the onset of AHA has been linked to the use of alemtuzumab (anti-CD52), nivolumab (PD-1 inhibitor) and TNFα inhibitors, particularly etanercept and infliximab, which are commonly prescribed for various autoimmune disorders." (PMID 38846411, 2024).
autoimmune disease (continued). "Since TNFα inhibitors, such as infliximab, etanercept, and adalimumab, are effective in RA and other autoimmune diseases, metformin's anti‐TNFα function could be effective in these diseases." (PMID 38311861, 2024). "The evaluated cytokines can be classified into three broad groups: the proinflammatory Th-1 cytokines: IL-2, IFN-γ, and TNF-α; the counterbalancing Th-2 cytokines: IL-4, IL-5, IL-10, and IL-13; and the Th-17 cytokine IL-17A, which is actively involved in several autoimmune diseases including MS." (PMID 38932415, 2024). "A recent study has demonstrated a highly dynamic pharmacokinetic of infliximab in patients with autoimmune disorders; patients with Crohn’s disease exhibited a higher terminal elimination half-life of the infliximab-TNF complex in comparison to patients with RA and ankylosing spondylitis." (PMID 38338832, 2024). "Additionally, TNFα, a central pro-inflammatory mediator involved in the pathogenesis of some inflammatory and autoimmune diseases, was notably reported to suppress Nrf-2 expression." (PMID 39174578, 2024). "Overall, TNF-α, IL-1β, and IL-6 could be valid molecular targets in light of their deregulation in autoimmune diseases and their involvement as activators of transduction cascades involving ADAM17." (PMID 39768182, 2024). "TNF is a pro-inflammatory cytokine involved in various autoimmune diseases; TNF inhibitors include the immunomodulatory agents infliximab and adalimumab that bind to TNF-α to prevent it from interacting with its receptors (such as the TNF-α receptor), thereby reducing inflammation." (PMID 39336171, 2024). "The SNPs at position TNF-α (-238 G/A, rs361525) and TNF-α (-308 G/A, rs1800629) are known to influence gene expression, which is linked to various infections and autoimmune diseases and the lack of association is noted." (PMID 38883059, 2024). "In a study, it was reported that in patients receiving anti-TNF-α therapy with an indication of autoimmune disease, 9 out of 23 patients (39%) who were HBsAg positive at the beginning of treatment developed HBVr, but none of the 178 HBsAg negative/anti-HBc positive patients developed HBVr7." (PMID 39045935, 2024). "Different subtypes of Transitional B cells also have different functions, for example, the T2/T3 type produces IL-10 to reduce CD4+ T-cell proliferation but, in some autoimmune diseases, Trb also secretes anti-inflammatory factors (IL-6 and TNF-α) that disrupt the Treg/Th17 balance." (PMID 38812518, 2024). "Moreover, the secretions of IL-6 and TNF-α played a role in the development of fatigue in both autoimmune and non-autoimmune diseases via neuroinflammation and neuroprogressive changes." (PMID 38903826, 2024). "Other studies suggested that regulating cytokine levels can help hosts alleviate diseases; for example, the TNF-α antagonist infliximab is currently used as a treatment for autoimmune diseases but is also being considered as a treatment for drug-resistant anxiety." (PMID 39339809, 2024). "These compounds effectively intervene in the overactive inflammation and immune responses characteristic of rheumatic and autoimmune diseases by modulating various signaling pathways, including the TNF, Toll-like, IL-6, RANKL, MAPK, PI3K/AKT/mTOR, JAK/STAT, and NRF2/GPX4 pathways." (PMID 39524446, 2024). "The loop involving B cells and plasma cells in the production of pro-inflammatory cytokines (IL-6 and TNF-α) and auto-antibodies, which can form immune complexes or bind directly to tissues, contributes to the development of autoimmune diseases, including thyroiditis and skin conditions." (PMID 39337081, 2024). "Th1 cells secrete cytokines such as IFN-g and TNF-a, promoting macrophage-induced resistance to infection and may contribute to autoimmune diseases in certain organs." (PMID 37193965, 2023).
autoimmune disease (continued). "TNF-α induces various cellular responses including cell survival, differentiation, and proliferation, regulates inflammatory responses, and is also involved in inflammatory and autoimmune diseases." (PMID 37687271, 2023). "Anti-TNF-α monoclonal antibodies (as potent, multifunctional, monoclonal antibodies) not only play an important role in the immune system’s homeostatic function but also exert excellent anti-inflammatory effects in various autoimmune diseases." (PMID 38004064, 2023). "However, Th 17 cells and their related cytokines, such as IL-6, IL-10, IL-17 and TNF-α, are important inflammatory mediators in autoimmune diseases, including uveitis, and are thought to drive intraocular inflammation." (PMID 38351911, 2023). "TNF, as an intracellular regulatory factor, is a signaling protein in autoimmune diseases." (PMID 36635624, 2023). "Biologics are used to treat many different autoimmune diseases by targeting inflammatory cytokines (TNF-α and IL-6) and cytokine receptors, interrupting the inflammatory vicious cycle, and are recommended even in early RA with low-severity inflammatory arthritis." (PMID 37763669, 2023). "Eiger is the homolog of tumor necrosis factor (TNF) in D. melanogaster, and members of the TNF family are important pleiotropic cytokines that play important roles in regulating infection, inflammation, autoimmune disease, and tissue homeostasis." (PMID 37818375, 2023). "However, dysregulated, continuous IL-6 and TNFα production is involved in various health diseases, such as autoimmune diseases, cancers and muscle wasting." (PMID 36830664, 2023). "Another study has suggested that vorinostat may considerably inhibit monocyte/macrophage activity by repressing Th1 and Th17 cells and reducing the TNF-α level in autoimmune diseases." (PMID 37762402, 2023). "Tumor necrosis factor-α (TNF-α) plays an important role in the pathogenesis of autoimmune diseases." (PMID 37214298, 2023). "Furthermore, we discuss the clinical applications of the IL-10:TNF-α ratio, using it as an predictor of pro- and anti-inflammatory treatment outcomes in autoimmune diseases and transplantation." (PMID 37180165, 2023). "TNF-α is recognized as a key factor that elevates the expressions of other pro-inflammatory cytokines in the early stages of autoimmune diseases and inflammatory responses, while MCP-1 serves as a chemokine that promotes monocyte infiltration and migration into damaged areas." (PMID 38004077, 2023). "Hence, although partially effective in various autoimmune diseases, anti-TNF therapies in MS patients seem to worsen pathology and clinical symptoms." (PMID 37138340, 2023). "Anti-TNFα agents are an approved therapeutic line in the treatment of autoimmune diseases and, although these agents have demonstrated safety and a good efficacy profile, some patients may experience adverse effects related to treatment administration." (PMID 36671633, 2023). "This in turn may explain some of the previous failings in modulating TNF activity in autoimmune disease, as well as strengthening the evidence that this novel combinatorial approach may serve as a new direction in TNF-targeting therapies." (PMID 37122019, 2023). "It has been demonstrated in another autoimmune disease that Hsp70 overly activates dendritic cells at the beginning phase of the disease and induces excessive TNF-α and Interleukin-17 (IL-17) release from these dendritic cells, with TLR4/nuclear factor-kappa B (NF-κB) pathway participation." (PMID 37108693, 2023). "Here we show that TTP/Zfp36 expression is indispensable for controlling TNFα levels in mammary cells, even in the absence of infection, mutations, or autoimmune diseases." (PMID 38274271, 2023). "Iatrogenic KS (iKS) is the term used to describe KS brought on by the use of steroids, immunosuppressive drugs, and agents with anti-tumor necrosis factor (TNF) activity in patients with autoimmune diseases, inflammatory diseases, or solid organ transplantation." (PMID 37849608, 2023).
autoimmune disease (continued). "Anti-TNFα biological agents are an important part of autoimmune diseases." (PMID 37554981, 2023). "TNFα is involved in the pathogenesis of multiple inflammatory or autoimmune diseases." (PMID 36902722, 2023). "Thus, selective inhibitors for TNFR1 are considered as next-generation anti-TNF treatment in autoimmune diseases." (PMID 36742332, 2023). "Anti-TNF-alpha agents have been hypothesized to display opposing effects on autoimmune disorders, having the ability to induce or treat such disorders, depending on the immunological profile and levels of IL-4 and IFN-gamma." (PMID 36615129, 2022). "Examples of such genes include IL4 in allergy and TNF in autoimmune diseases." (PMID 35513850, 2022). "Notably, considering immunocompromised patients due to autoimmune diseases on anti-TNF treatment, the seroconversion prevalence was estimated as 86.07% (95% CI: 63.16%; 99.23%, test of heterogeneity: I2 = 99.1%, p < 0.01)." (PMID 35941646, 2022). "However, TNFα exerts a pro‐inflammatory action, especially in autoimmune diseases such as Crohn's disease, and TNFα has become a major therapeutic target." (PMID 35916639, 2022). "The inappropriate activation of TNF-α signaling can contribute to autoimmune diseases." (PMID 35990826, 2022). "Although very rare, new-onset or exacerbations of vitiligo can occur in the anti‐TNF‐α treatment of other autoimmune diseases, the risk of which must not be ignored." (PMID 36119071, 2022). "TNF is related to various diseases such as allergy, autoimmune diseases, and tumors." (PMID 35879791, 2022). "TNF inhibitors are widely used to treat inflammatory diseases; however, 30%–50% of treated patients develop new autoantibodies, and 0.5%–1% develop secondary autoimmune diseases, including lupus." (PMID 35104241, 2022). "Conversely, multiple studies have shown that patients with autoimmune disorders who are treated with the current generation of general TNF inhibitors (e.g., etanercept, infliximab, adalimumab) are at increased risk of tuberculosis and certain malignancies including melanoma." (PMID 35879777, 2022). "Indeed, it shares many features with other autoimmune diseases such as mechanisms of chronic inflammation, a major role of TNFα in its pathogenesis and an involvement of gene loci similar to those of other autoimmune diseases." (PMID 35812457, 2022). "Anti-TNF therapy has become a mainstay treatment for some autoimmune diseases." (PMID 36358977, 2022). "TNFα exhibits toxicity under a variety of autoimmune disease conditions, and so understanding its release could help control these toxic effects." (PMID 36214107, 2022). "TNF-α was initially thought to contribute to tumor necrosis, but it has recently been found to have additional important functions as a pathological component of autoimmune diseases." (PMID 36293806, 2022). "TNF-α contributes to the pathogenesis of the autoimmune disease LN." (PMID 35804318, 2022). "Tumor necrosis factor α (TNF-α) plays an important role in pathogenesis of autoimmune diseases." (PMID 35844555, 2022). "Nie screened a sdAbs called NT-3 that can effectively inhibit the tumor necrosis factor TNF-α, which could induce autoimmune diseases and inflammation, with an IC50 of 0.804 μM." (PMID 36479130, 2022). "TNF is a pro-inflammatory cytokine critically involved in autoimmune diseases." (PMID 35122118, 2022). "MIF is known to induce the expression of key proinflammatory genes, including IL-1, TNF, IL-6, IL-8, COX-2, and MMPs, and has been implicated in the development of many acute inflammatory and autoimmune diseases as well as chronic inflammatory metabolic disorders." (PMID 34445689, 2021). "Patients with autoimmune diseases on anti-TNF have had reduced serum levels of TNF-α and IL-6." (PMID 33995033, 2021). "Furthermore, disruption of Rubicon leads to upregulation of IL‐1β, IL6 and TNF‐α secretion, and the mice fail to gain weight and develop an autoimmune disease that resembles systemic lupus erythematosus." (PMID 33586810, 2021).
autoimmune disease (continued). "The NF-κB pathway has long been proposed as a therapeutic target in inflammatory and autoimmune diseases, but complete inhibition of TNF-α using neutralizing reagents has resulted in disease exacerbation, risk of infection, and other side effects related to immune regulation and tissue regeneration." (PMID 34291056, 2021). "Blocking TNF-α causes a decline in IL-1 and IL-6, as well as adhesion molecules and vascular endothelial growth factors (VEGFs), and in disorders such as autoimmune diseases, TNF blockers are being suggested to be used in hospitalized patients with severe inflammatory response." (PMID 33946736, 2021). "Under inflammatory conditions, such as autoimmune diseases and allergy, it has been shown that several cytokines (IL-4, TNF-α, and IL-6) may be involved in downmodulation of Treg suppression." (PMID 34777330, 2021). "On this basis, we speculated that TNF-α -308A may also have a similar role in autoimmune diseases such as AS, RA, and PsA." (PMID 35126146, 2021). "The identification of WFA-interactome associated via ZAP70, TCR, and NFκB in T-cells could be important in understanding T-cell dysfunctions acquired through prolonged exposure to TNF-α in autoimmune diseases." (PMID 34742736, 2021). "However, treatment of certain autoimmune disorders with TNF antagonists suggested that TNF can take part in tumor suppression." (PMID 33917839, 2021). "The risk of bone loss and fracture is increased in individuals with RA and other autoimmune diseases because OCs, mediated by inflammatory factors, such as TNFα and IL-1β, induce not only erosion of cartilage and bone locally in affected joints, but also degradation of bone systemically." (PMID 35011694, 2021). "In the case of patients with autoimmune diseases, treatments are based on drugs such as anti-TNF agents and interleukin-6 receptor blockers, thus favoring the onset of infections by blocking the signal transduction from the cell surface receptors to the nucleus." (PMID 35054223, 2021). "Moreover, since TNF inhibitors are widely used to treat autoimmune disorders, it is important to address possible side effects of anti-TNF therapy." (PMID 34054827, 2021). "In some situations, Treg defects can be reversed by successful treatment of autoimmune disease, particularly RA, by neutralization of cytokines (such as TNF or IL-6) that can impair Treg differentiation and/or functional effectiveness, but similar studies have not been reported in SSc." (PMID 33407866, 2021). "However, TAK-1 inhibitor Takinib has been shown to broaden the therapeutic potential of anti-TNF approaches in cancer and autoimmune disease, and we anticipate that it is going to be developed for clinical testing." (PMID 34271980, 2021). "Additionally, we reported that the anti-TNF-α agents, which are considered the cornerstone in treating autoimmune diseases, increased MAP viability in MAP infected macrophages." (PMID 34025650, 2021). "Abnormally high TNF-α production is observed in several autoimmune diseases including SLE." (PMID 34768756, 2021). "Moreover, several previous studies have illustrated that activated NF-κB regulates the expression of genes such as IL-1β, IL-6, and TNF-α and promotes the occurrence, development and pathogenesis of autoimmune diseases, chronic infections and cancer." (PMID 34017253, 2021). "Similar attenuation was observed for IL-1α and TNFα after LPS stimulation in haplotype 2A patients, which correlates with mutations in the NLRP1 gene that are associated with a high risk of autoimmune diseases, such as vitiligo, Addison’s disease, and type 1 diabetes." (PMID 35069570, 2021). "Tumor necrosis factor alpha (TNF-α) was initially recognized as a factor that causes the necrosis of tumors, but it has been recently identified to have additional important functions as a pathological component of autoimmune diseases." (PMID 33800290, 2021).